NFAM1 (NFAT activating protein with ITAM motif 1)
Description:
May function in immune system as a receptor which activates via the calcineurin/NFAT-signaling pathway the downstream cytokine gene promoters. Activates the transcription of IL-13 and TNF promoters. May be involved in the regulation of B-cell, but not T-cell, development. Overexpression activates downstream effectors without ligand binding or antibody cross-linking.
Synonyms: CNAIP
Tractability: Antibody: its Gene Ontology location is reachable by antibodies, with high confidence; UniProt places it where antibodies can reach, with medium confidence; UniProt predicts a signal peptide or a membrane-spanning region; the Human Protein Atlas places it where antibodies can reach. PROTAC: ubiquitination databases record sites on it; its protein half-life has been measured.
Gene: Protein-coding gene on chromosome 22 (42,380,407 to 42,432,403, reverse strand). Ensembl gene ENSG00000235568.
Subcellular location: Cell membrane
Subcellular location (Human Protein Atlas): Cytosol; Plasma membrane
Pathways (Reactome):
Immune System: Neutrophil degranulation
Gene Ontology:
Molecular function: protein binding; transmembrane signaling receptor activity
Biological process: calcineurin-NFAT signaling cascade; intracellular signal transduction; signal transduction; B cell differentiation; B cell receptor signaling pathway; inflammatory response; positive regulation of cytokine production; cell surface receptor signaling pathway; positive regulation of B cell receptor signaling pathway; regulation of B cell differentiation
Cellular component: membrane; azurophil granule membrane; membrane raft; plasma membrane
Genetic constraint (gnomAD): Loss-of-function variants: 8 observed, 12.93 expected, observed/expected ratio (o/e) 0.62, 90% interval 0.36 to 1.12. The upper end of that interval is the gene's LOEUF score, 1.12, which puts it in group 4 of 6, group 1 being the genes least tolerant of losing a copy. Missense variants: 176 observed, 194.49 expected, observed/expected ratio (o/e) 0.9, 90% interval 0.8 to 1.02. Synonymous variants: 103 observed, 85.66 expected, observed/expected ratio (o/e) 1.2, 90% interval 1.02 to 1.42.
Homologues: Orthologues: chimpanzee NFAM1 (98% identical), macaque NFAM1 (87% identical), pig NFAM1 (62% identical), dog NFAM1 (58% identical), guinea pig NFAM1 (57% identical), rat Nfam1 (50% identical), mouse Nfam1 (47% identical).
Diseases named in the same sentence as NFAM1 in open-access papers:
NFAM1 is named in the same sentence as 14 diseases in open-access papers, as found by Europe PMC text mining. Sharing a sentence is not in itself a finding about the gene and the disease. The quoted sentences say what the papers report.
coronary artery disease (2 papers, 2021). "Recently, NFAT activating protein with ITAM motif 1 (NFAM1), which is associated with monocyte recruitment, has been identified as novel mediator affecting pathobiological progression of coronary artery disease." (PMID 34796212, 2021). "Recent studies have linked NFAM1 expression to multiple diseases, including coronary artery disease and Paget’s disease of bone." (PMID 35095847, 2021). "In further evidence of a link to disease, NFAM1 expression was recently reported to be upregulated in peripheral blood monocytes from patients with coronary artery disease (CAD)." (PMID 35095847, 2021).
autoimmune disease (1 paper, 2021). A disorder resulting from loss of function or tissue destruction of an organ or multiple organs, arising from humoral or cellular immune responses of the individual to their own tissue constituents. "Taken together, we conclude that NFAM1 functions to amplify cytokine production and should be further evaluated as a therapeutic target for treatment of autoimmune disease." (PMID 35095847, 2021). "This novel role of NFAM1 warrants further investigation into the role of NFAM1 in additional autoimmune diseases." (PMID 35095847, 2021).
cardiac amyloidosis (1 paper, 2022). Cardiac amyloidosis is a condition whereby cardiac tissue is infiltrated by amyloid fibrils. "miR-342-3p, which was revealed to interact with NFAM1 in our work, has been found to be differently expressed in blood-based miRNA profiles of cardiac amyloidosis, dilated cardiomyopathies, and heart failure in CVD research studies." (PMID 35615580, 2022).
colitis (1 paper, 2021). Inflammation of the colon. "Lastly, to assess the role of NFAM1 in IBD, we compared development of anti-CD40 induced colitis in NFAM1+/+ and NFAM1-/- mice." (PMID 35095847, 2021). "Lastly, we investigated the role of NFAM1 in promoting colitis in vivo." (PMID 35095847, 2021). "Lastly, we tested the impact of NFAM1 deletion on development of anti-CD40 induced colitis." (PMID 35095847, 2021). "The anti-CD40 colitis model is run on a RAG-/- background, we therefore first generated NFAM1+/+ RAG-/- and NFAM1-/- RAG-/- mice." (PMID 35095847, 2021). "For one, our in vitro experiments focused on the role of NFAM1 in monocytes, while there are multiple cell types that contribute to anti-CD40 colitis, not all of which may be impacted by NFAM1 deletion." (PMID 35095847, 2021). "Despite the role of NFAM1 in promoting CD40L-mediated activation, NFAM1-/- mice are not protected against development of anti-CD40 colitis." (PMID 35095847, 2021).
Crohn disease (1 paper, 2021). A gastrointestinal disorder characterized by chronic inflammation involving all layers of the intestinal wall, noncaseating granulomas affecting the intestinal wall and regional lymph nodes, and transmural fibrosis. "We performed expression analysis of NFAM1 using publicly available gene expression data sets and found that NFAM1 expression is significantly induced in intestinal biopsies from Crohn’s disease (CD) and ulcerative colitis (UC) patients." (PMID 35095847, 2021).
Paget’s disease of bone (1 paper, 2021). "For example, NFAM1 expression is upregulated in Paget’s disease of bone (PDB), a disease that is characterized by excessive bone resorption via abnormal osteoclasts." (PMID 35095847, 2021).
parasitic diseases (1 paper, 2018). "These cattle are known to be tolerant to different endemic parasitic diseases, and so the immunity-related genes within the candidate regions identified (e.g. LTA4H, IL7, IL15, FCN, LTA4H and NFAM1) are potential targets of natural selection." (PMID 30114214, 2018).
NFAM1 also shares sentences with these, for which no sentence is quoted: asthma (1 paper); dilated cardiomyopathies (1); heart failure (1); intellectual impairment (1); mammary tumors (1); renal adysplasia (1); ulcerative colitis (1).